PYURF (PIGY upstream open reading frame)
Description:
In mitochondria, S-adenosylmethionine-dependent methyltransferase chaperone that supports both coenzyme Q biosynthesis, by stabilizing its components, such as COQ5, and NADH:ubiquinone oxidoreductase complex (complex I, MT-ND1) assembly, by stabilizing complex I assembly factors, such as NDUFAF5.
Synonyms: NDUFAFQ; PREY
Tractability: PROTAC: ubiquitination databases record sites on it.
Gene: Protein-coding gene on chromosome 4 (88,520,998 to 88,523,776, reverse strand). Ensembl gene ENSG00000145337.
Subcellular location: Mitochondrion
Subcellular location (Human Protein Atlas): Nucleoplasm
Pathways (Reactome):
Metabolism: Complex I biogenesis
Gene Ontology:
Molecular function: protein binding
Biological process: protein stabilization
Cellular component: endoplasmic reticulum membrane; mitochondrion
Genetic constraint (gnomAD): Loss-of-function variants: 9 observed, 8.36 expected, observed/expected ratio (o/e) 1.08, 90% interval 0.64 to 1.76. That is too few expected variants to judge how well the gene tolerates losing a copy. Missense variants: 130 observed, 150.08 expected, observed/expected ratio (o/e) 0.87, 90% interval 0.75 to 1. Synonymous variants: 56 observed, 62.19 expected, observed/expected ratio (o/e) 0.9, 90% interval 0.73 to 1.12.
Homologues: Orthologues: chimpanzee PYURF (98% identical), macaque PIGY (83% identical), dog PYURF (82% identical), guinea pig PYURF (75% identical), rat Pyurf (68% identical), tropical clawed frog pyurf (54% identical), zebrafish PYURF (47% identical).
Diseases named in the same sentence as PYURF in open-access papers:
PYURF is named in the same sentence as 6 diseases in open-access papers, as found by Europe PMC text mining. Sharing a sentence is not in itself a finding about the gene and the disease. The quoted sentences say what the papers report.
Anxiety (1 paper, 2021). Intense feelings of nervousness, tension, or panic often arise in response to interpersonal stresses. "The significant weaning and MIA effects detected for PYURF are consistent with reports that this gene was under-expressed in the amygdala of low-novelty responder rats modeling anxiety-like behaviors relative to high novelty responders." (PMID 33856433, 2021).
metabolic acidosis (1 paper, 2025). "Interestingly, the only reported case of pathogenic human PYURF variants presented neonatally with profound metabolic acidosis and multisystem mitochondrial disease, which included optic atrophy, a similar clinical presentation to RTN4IP1 deficiency." (PMID 40859035, 2025).
PYURF also shares sentences with these, for which no sentence is quoted: bacterial infections (1 paper); mitochondrial disease (1); neurological disorders (1); optic atrophy (1).